U8 (U8 small nucleolar RNA )
Synonyms: LOC124900553
Gene: Small nucleolar RNA gene on chromosome 3 (41,899,111 to 41,899,253, reverse strand). Ensembl gene ENSG00000212145.
Gene Ontology:
Biological process: RNA processing
Cellular component: nucleolus
Homologues: Orthologues: chimpanzee U8 (100% identical), macaque U8 (70% identical), rabbit U8 (52% identical). Paralogues in human: U8 (66% identical), U8 (65% identical), U8 (64% identical), U8 (61% identical), U8 (59% identical), U8 (57% identical), U8 (55% identical), U8 (53% identical), U8 (52% identical), U8 (34% identical).